HOXC6 (homeobox C6)
Diseases named in the same sentence as HOXC6 in open-access papers (continued):
Sharing a sentence is not in itself a finding about the gene and the disease.
glioma (continued). "In addition, knockdown of HOXC6 inhibited the proliferation of glioma cells." (PMID 35488304, 2022). "Since previous experimental data showed a relationship between HOXC6 expression and glioma biological progression as well as the immune response, we further considered whether the expression of HOXC6 was relevant to the formation of the tumour immune microenvironment." (PMID 35488304, 2022). "However, the exact mechanism by which HOXC6 regulates glioma tumorigenesis is still unclear." (PMID 35432534, 2022). "However, there are few studies regarding the HOXC6 gene in glioma cells." (PMID 35571491, 2022). "Furthermore, we used RNA interference (RNAi) to knock down HOXC6 in U251 and U87 glioma cells." (PMID 35571491, 2022). "HOXC6 was also found to regulate EMT signaling, and was proposed as a new immunotherapeutic target for gliomas." (PMID 38499392, 2024). "In conclusion, an immune signature based on HOXC6, WT1, CD70, and OTP expression was shown to serve as an independent and specific prognostic indicator for patients with TERTp- mutant gliomas." (PMID 38499392, 2024). "We also used this database to analyze 518 low-grade gliomas (LGG, WHO I-II) and 207 normal brain tissues and showed that HOXC6 was still expressed at high levels in LGG (p < 0.05)." (PMID 35571491, 2022). "In our study, the Spearman correlation coefficients between HOXC6 and PD-L1 were 0.44 in TCGA gliomas and 0.42 in CGGA gliomas." (PMID 35488304, 2022). "Next, the protein levels of HOXC6 in human SHG44, H4, U87, A172, and U251 glioma cells were measured by Western blot." (PMID 35571491, 2022). "In conclusion, a risk model constructed by 6 hypoxia-driven genes (WT1, HOXA2, HOXC6, MMP9, SHOX2 and MYOD1) provide valuable clinical utility for the prognostic prediction of glioma patients." (PMID 36118887, 2022). "Our research focused on HOXC6 as a key factor influencing the EMT-related invasion and migration of gliomas and an immune-related biomarker." (PMID 35488304, 2022). "Heatmap analysis showed that WT1, HOXA2, HOXC6, MMP9 and SHOX2 are highly expressed in high-hypoxia glioma tissues in the TCGA, whereas MYOD1 expression is reduced." (PMID 36118887, 2022). "Interesting, in the current study, we found that HOXC6, MMP9 and SHOX2 expression were increased in the glioma tissues with promoter unmethylation of MGMT, while MYOD1 was reduced." (PMID 36118887, 2022). "Higher expression levels of HOXC6, MMP9 and SHOX2, and lower expression levels of MYOD1 were observed in the glioma tissues with promoter-unmethylation of MGMT in TCGA." (PMID 36118887, 2022). "We first determined the expression HOXC6, MMP9, SHOX2 and MYOD1 in glioma tissues with promoter-methylation and promoter-unmethylation of MGMT." (PMID 36118887, 2022). "In the present study, through perform IHC, we found that high expression of HOXC6, MMP9 and SHOX2 and low expression of MYOD1 were observed in recurrent glioma tissues." (PMID 36118887, 2022). "Interesting, through multivariate COX regression analysis, we found that HOXC6, MMP9, SHOX2 and MYOD1 can act as independent prognostic factors for glioma." (PMID 36118887, 2022). "Based on the glioma database analyses, GBM patients with significantly increased HOXC6 expressions showed significantly lower prognosis and survival compared to those with relatively low HOXC6 expressions." (PMID 35571491, 2022). "Among the seven key genes (HOXD11, HOXC9, HOXC6, HOXA3, FBXO39, OTP, and HMGA2) consistently detectable in both normal astrocyte cell lines (SVG-P12) and glioma cell lines (U87, U251, LN229), tumor cell lines exhibited significantly upregulated expression compared to normal cell lines." (PMID 41049291, 2025). "HOXC6 was found to be overexpressed in clinical glioma samples, and its knockdown stimulated the WIF-1/Wnt signaling pathway and induced cell cycle arrest and apoptosis in U87 glioma cells." (PMID 38499392, 2024).
glioma (continued). "Similarly, we found that the expression of HOXC6, MMP9 and SHOX2 was higher in recurrent glioma tissues compared with primary glioma tissues and the expression of MYOD1 was decreased, while there were no significant changes in WT1 and HOXA2." (PMID 36118887, 2022). "Importantly, we found that CD133 expression in glioma was highly correlated with the expression of HOX gene stem cell factors (HOXA5, HOXA7, HOXA10, HOXC4 and HOXC6)." (PMID 28055976, 2017). "HOXC6 might be a key factor in promoting tumorigenesis and glioma progression by regulating the EMT signaling pathway and might represent a novel immune therapeutic target in gliomas." (PMID 37547473, 2023). "Moreover, we found that HOXC6 was significantly upregulated in high-grade glioma, a wild-type IDH gene and 1p19q non-codeletion, and these characteristics indicate tumour malignancy and are insensitive to chemotherapy." (PMID 35488304, 2022). "According to the TCGA database, gliomas with a wild-type IDH gene and gliomas without 1p/19q codeletion had a high level of HOXC6 expression consistent with the group of gliomas with a mutant-type IDH gene and with 1p/19q codeletion." (PMID 35488304, 2022).
hepatocellular carcinoma (13 papers, 2018 to 2022). A malignant tumor that arises from hepatocytes. "A previous report revealed that miR-147-mediated HOXC6 silencing can inhibit cell proliferation and migration in hepatocellular carcinoma in vitro." (PMID 32171324, 2020). "miR-147 can suppresses human hepatocellular carcinoma migration, chemosensitivity, and proliferation by inhibiting HOXC6." (PMID 32398967, 2020). "In hepatocellular carcinoma, HOXC6 overexpression promoted cell proliferation, while siRNA-mediated HOXC6 down-regulation not only inhibited proliferation and migration but also increased 5-FU chemosensitivity." (PMID 30886783, 2019). "Consistently with our results, knockout of HOXC6 inhibited cell migration and proliferation in hepatocellular carcinoma." (PMID 30559605, 2018). "Aberrant expression of HOXC6 has been reported in several malignant tumors, yet little is known about the value of HOXC6 in invasion and prognosis of hepatocellular carcinoma (HCC)." (PMID 29348394, 2018). "Aberrant expression of HOXC6 may result in the malignant transformation of normal cells, and elevated HOXC6 expression has been observed in several types of cancers, including prostate, gastrointestinal, colorectal, and hepatocellular cancers." (PMID 30993034, 2019). "For example, homeobox C6 (HOXC6), one of the candidate genes, contributes to invasion by inducing the EMT pathway in hepatocellular carcinoma, oral squamous cell carcinoma, and cervical cancer." (PMID 34083586, 2021).
breast cancer (12 papers, 2011 to 2023). A primary or metastatic malignant neoplasm involving the breast. "HOXC6 overexpression triggers expression of tumor growth factor and associates with breast cancer." (PMID 33330580, 2020). "HOXC6 is aberrantly expressed in head and neck squamous cell carcinoma, gastrointestinal malignancies, and breast cancer." (PMID 38012642, 2023). "Similar to HOXA10, HOXB9 and HOXC6 also play a physiological role in mammary gland development and are also overexpressed in several tumors, including breast cancer." (PMID 32796699, 2020). "Several authors indicate that BPA increases HOXB9 and HOXC6 expression both in cultured human breast cancer cells (MCF7) and in the mammary glands of ovariectomized rats (25 μg/kg), suggesting these transcription factors as mediators of BPA harmful effects in breast tumor." (PMID 32796699, 2020). "Furthermore, HOXC6 is involved in various cancers including lung cancer, osteosarcomas and breast cancer." (PMID 30559605, 2018). "With regard to this, recently performed in vitro and in vivo experiments showed that Homeobox C6 (HOXC6) is an estrogen-regulated gene in breast cancer cells which expression may be induced by exposure to estrogenic EDCs such as BPA, in competition with estradiol (E2)." (PMID 29865233, 2018). "In this regard, it was recently reported that the homeobox (HOX)-containing gene HOXC6, a critical player in mammary gland development and milk production, is transcriptionally activated via coordination of KMT2D and ER in an estrogen environment in breast cancer and placental choriocarcinoma cells." (PMID 24633898, 2014).
colon carcinoma (11 papers, 2009 to 2025). "HOXC6 expression was higher and negatively associated with prognosis in right-sided colon cancer than in left-sided colon cancer." (PMID 35836930, 2022). "In CRC, MMP1 derived from tumor-associated macrophages promotes the cell cycle transition from G0/G1 to S and G2/M phases, and the overexpression of HOXC6 induces EMT in colon cancer cells." (PMID 38443703, 2024). "The overexpression of HOXC6 can promote the migration and invasion of colon cancer cells by inducing epithelial-mesenchymal transition (EMT) via activating the Wnt/β-catenin signaling pathway." (PMID 35711425, 2022). "Furthermore, upregulation of HOXC6 was observed in right-sided colon cancers and lower expression in left-sided colons and rectal cancers was associated with poor prognosis." (PMID 38532103, 2024). "Furthermore, overexpression of HOXC6 promoted the migration and invasion of colon cancer cells through inducing EMT by activating the Wnt/β-catenin signaling pathway and inhibition of DKK1 secretion." (PMID 33795652, 2021). "The top two genes identified to be differentially expressed between rectal and colon cancers were HOX family genes: HOXB13 was upregulated and HOXC6 downregulated in the rectal cancer samples." (PMID 38532103, 2024). "IHC images of HOXC6 in colon cancer were not available in HPB database, we compared the expression differences of other four signature genes at protein levels, the expression levels were consistent with the results of qRT-PCR." (PMID 37007145, 2023). "Similar results were found that elevated BST2 level, HOXC6, and TNNT1 level are correlated with poor prognosis in colon cancer patients, while TNNT1 protein may be mediated through the process of epithelial–mesenchymal transition." (PMID 34381786, 2021).
lung carcinoma (10 papers, 2013 to 2024). "HOXC6 (homeobox C6) is overexpressed in lung cancer, regulating the expression of genes related to cell proliferation, migration, and invasion in NSCLC." (PMID 36661515, 2023). "Analysis of publicly available data revealed that there was a 5-fold and 8.8-fold increase in the expression of HOXC6 in 2 independent lung cancer datasets, GSE30219 and GSE27262, respectively." (PMID 30993034, 2019). "Furthermore, the overexpression of HOXC6 has been detected in several human carcinomas, including breast, gastrointestinal, and lung cancers, as well as leukemia." (PMID 33076847, 2020). "We examined the expression level of HOXC6 in lung cancer using in silico approaches." (PMID 30993034, 2019). "In addition, bioinformatics analyses showed that HOXC6 may enhance lung cancer progression by regulating the expression of pro-tumorigenic genes involved in proliferation, migration, and invasion." (PMID 30993034, 2019). "According to the TRN of lung cancer, SOX4, FOXM1, ETV4, HOXC6, and E2F3 are the main positive regulators, whereas SOX17, KLF4, and ZBTB16 are the main negative regulators of transcription, controlling the expression of other TFs and target genes in lung cancer." (PMID 39228892, 2024). "Quantitative real‐time RT‐PCR (qRT‐PCR) analyses of total RNA isolates generated from directly ex vivo isolated normal lung or lung carcinoma tissues revealed a significant upregulation of HOXB7 and HOXC6, as well as HOXC8 mRNA by tendency expression in the NSCLC tissues." (PMID 32830458, 2021). "HOXC6 is highly expressed in NSCLC, and it may enhance lung cancer progression by regulating the expression of pro-tumorigenic genes involved in proliferation, migration, and invasion." (PMID 30993034, 2019). "According to the TRN analysis, SOX4 can be regulated by HOXC6, whereas DLX5 can be regulated by SOX4, FOXM1, and ETV4, and according to the co-regulatory network analysis, they both participate in the formation of TF complexes in both subtypes of lung cancer (NSCLC and SCLC)." (PMID 39228892, 2024). "HOXC6 and RFX2 are also deregulated in eight sets of lung cancer as FOXF1 and none of the other types of cancer." (PMID 36101460, 2022).
glioblastoma (8 papers, 2013 to 2025). The most malignant astrocytic tumor (WHO grade IV). "HOXC6 has been shown to facilitate the proliferation and migration of glioblastoma cells by activating the ERK/MAPK signaling pathway." (PMID 35547861, 2022). "HOXC6 was of significant prognostic value in patients with glioblastoma in the Cancer Genome Atlas (TCGA) microarray dataset, and this finding was validated by additional public datasets." (PMID 35432534, 2022). "HOXC6 knockdown suppressed glioblastoma cell growth in vivo, according to the tumor volume analyses." (PMID 35571491, 2022). "HOXC6 expression has a significant prognostic value and is related to the cell cycle process in glioblastoma." (PMID 35432534, 2022). "In conclusion, HOXC6 might be a candidate biomarker gene for individual treatment optimization of glioblastoma." (PMID 35432534, 2022). "We compared the expression level of HOXC6 across four glioblastoma subtypes (classical, mesenchymal, neural, and proneural) and found that only the proneural subtype had a significant heterogeneity in the expression levels of HOXC6 among four glioblastoma subtypes (p = 0.003, t-test)." (PMID 35432534, 2022). "Bioinformatic analysis suggested that the HOXC6 might be involved in the cell cycle-related biological processes and pathways that are well established in the context of glioblastoma tumorigenesis." (PMID 35432534, 2022). "in 2021 found that the prognosis of glioblastoma (GBM) can be determined by seven differentially expressed genes (DEGs) 47, namely CLEC5A, HOXC6, HOXA5, CCL2, GPRASP1, BSCL2, and PTX3." (PMID 39132508, 2024).
head and neck squamous cell carcinoma (7 papers, 2014 to 2026). A squamous cell carcinoma that arises from any of the following anatomic sites: lip and oral cavity, nasal cavity, paranasal sinuses, pharynx, larynx, and salivary glands. "Anti-apoptotic roles for HOXC6 have also been described in head and neck squamous cell carcinoma in which HOXC6 directly increases the promoter activity causing overexpression of Bcl-2." (PMID 24708576, 2014). "Overexpressed HOXC6 is found in human head and neck squamous cell carcinoma cell lines and promote proliferation." (PMID 30559605, 2018). "HOXC6 is also deregulated in human head and neck squamous cell carcinoma and modulates Bcl-2 expression." (PMID 27081081, 2016). "In head and neck squamous cell carcinoma, HOXC6 inhibits apoptosis via Bcl-2 regulation." (PMID 27081081, 2016). "In our previous studies, HOXC6 was identified as being overexpressed in head and neck squamous cell carcinoma (HNSCC) tissue and cell lines." (PMID 35008435, 2021).
laryngeal carcinoma (6 papers, 2020 to 2025). Carcinoma that arises from the laryngeal epithelium. "In laryngeal carcinomas, homeobox C6 (HOXC6) and the TGF-β signaling pathway promote EMT and lymph node metastasis; the overexpression of IL-22 and IL-22R1 was correlated with metastasis to the lymph node and clinical stages." (PMID 35740551, 2022). "Upregulated miRNA-141 contributes to suppressing EMT and lymph node metastasis in laryngeal cancer through HOXC6-dependent TGF-β signaling pathway." (PMID 33628829, 2021). "The blockade of HOXC6-dependent TGF-β signaling pathway is responsible for the suppressed EMT and lymph node metastasis in laryngeal cancer." (PMID 32171324, 2020). "The researchers discovered that upregulation of miR-141 led to a downregulation of HOXC6 and subsequent inhibition of the TGF-β signaling pathway, which effectively repressed EMT and reduced the viability, migration, and invasion abilities of laryngeal cancer cells, as well as tumor growth in vivo." (PMID 40277812, 2025).
prostate tumors (6 papers, 2011 to 2022). "The top 2 TFs associated with the most tumor-specific enhancer probes in prostate tumors, HOXC6 and DLX1, are each associated with more than 100 tumor-specific enhancer probes." (PMID 27833659, 2016). "In a previous study, the investigators found that HOXC6 and DLX1 associate with different prostate tumor-specific enhancer clusters and confer distinct transcriptomic changes on C42B prostate cancer cells, which play a role in prostate tumor development." (PMID 36304471, 2022). "Using DNA methylation data from The Cancer Genome Atlas (TCGA), we have previously identified HOXC4 and HOXC6 in the set of top-ranked transcription factors (TFs) whose high expression correlates with the creation of prostate tumor-specific enhancers." (PMID 32012197, 2020). "Pathway analysis revealed that genes whose expression is positively regulated by HOXC4 and HOXC6 in prostate tumor cells are related to cancer and the cell cycle." (PMID 32012197, 2020). "Homeobox C6 (HOXC6) is reportedly overexpressed in breast, lung and prostate tumors, along with leukemia, osteosarcomas and medulloblastomas." (PMID 27081081, 2016). "RNA-seq analysis reveals that, similar to our previous analysis of prostate tumors, HOXC4 and HOXC6 are robustly expressed in 22Rv1 cells." (PMID 32012197, 2020). "Several transcription factors, including NKX3-1, HOXB13, HOXC6, HOXD11 and HOXD13, were also found to have deregulated expression in the stromal reaction to invasive prostate tumors." (PMID 21611158, 2011). "Interestingly, HOXC6 and DLX1, which we characterized above, were also found in these “common” links, suggesting that they may play a role in the development of the majority of prostate tumors." (PMID 27833659, 2016). "We further characterized several transcription factors linked to a large number of enhancers in each tumor type, including GATA3 in non-basal breast tumors, HOXC6 and DLX1 in prostate tumors, and ZNF395 in kidney tumors." (PMID 27833659, 2016).
leukemia (5 papers, 2013 to 2023). A malignant (clonal) hematologic disorder, involving hematopoietic stem cells and characterized by the presence of primitive or atypical myeloid or lymphoid cells in the bone marrow and the blood. "Among the upregulated probesets were two homeobox genes, HOXC6, a transcription factor expressed in the developing skeleton, and HOXA9, a transcription factor involved in myeloid differentiation linked with increased cell proliferation in leukaemia." (PMID 24148222, 2013).